RPS6KB1 (ribosomal protein S6 kinase B1)
Description:
Serine/threonine-protein kinase that acts downstream of mTOR signaling in response to growth factors and nutrients to promote cell proliferation, cell growth and cell cycle progression. Regulates protein synthesis through phosphorylation of EIF4B, RPS6 and EEF2K, and contributes to cell survival by repressing the pro-apoptotic function of BAD. Under conditions of nutrient depletion, the inactive form associates with the EIF3 translation initiation complex. Upon mitogenic stimulation, phosphorylation by the mechanistic target of rapamycin complex 1 (mTORC1) leads to dissociation from the EIF3 complex and activation. The active form then phosphorylates and activates several substrates in the pre-initiation complex, including the EIF2B complex and the cap-binding complex component EIF4B. Also controls translation initiation by phosphorylating a negative regulator of EIF4A, PDCD4, targeting it for ubiquitination and subsequent proteolysis. Promotes initiation of the pioneer round of protein synthesis by phosphorylating POLDIP3/SKAR. In response to IGF1, activates translation elongation by phosphorylating EEF2 kinase (EEF2K), which leads to its inhibition and thus activation of EEF2. Also plays a role in feedback regulation of mTORC2 by mTORC1 by phosphorylating MAPKAP1/SIN1, MTOR and RICTOR, resulting in the inhibition of mTORC2 and AKT1 signaling. Also involved in feedback regulation of mTORC1 and mTORC2 by phosphorylating DEPTOR. Mediates cell survival by phosphorylating the pro-apoptotic protein BAD and suppressing its pro-apoptotic function (By similarity). Phosphorylates mitochondrial URI1 leading to dissociation of a URI1-PPP1CC complex. The free mitochondrial PPP1CC can then dephosphorylate RPS6KB1 at Thr-412, which is proposed to be a negative feedback mechanism for the RPS6KB1 anti-apoptotic function. Mediates TNF-induced insulin resistance by phosphorylating IRS1 at multiple serine residues, resulting in accelerated degradation of IRS1. In cells lacking functional TSC1-2 complex, constitutively phosphorylates and inhibits GSK3B. May be involved in cytoskeletal rearrangement through binding to neurabin (By similarity). Phosphorylates and activates the pyrimidine biosynthesis enzyme CAD, downstream of MTOR. Following activation by mTORC1, phosphorylates EPRS and thereby plays a key role in fatty acid uptake by adipocytes and also most probably in interferon-gamma-induced translation inhibition.
Synonyms: S6K-beta-1; S6K1; p70 S6KA; STK14A; p70(S6K)-alpha; PS6K; S6K; p70-S6K; p70-alpha
Tractability: Small molecule: a drug acting on it is in phase 1 trials; a structure with a bound ligand is known; a high-quality ligand is known; it has a binding pocket of medium quality; it belongs to a druggable protein family. PROTAC: it is named in the literature on targeted protein degradation; ubiquitination databases record sites on it; its protein half-life has been measured; a small molecule that binds it is known.
Target class: Enzyme; Protein Kinase; AGC protein kinase p70 subfamily; Kinase; AGC protein kinase group; AGC protein kinase RSK family
Gene: Protein-coding gene on chromosome 17 (59,893,046 to 59,950,574, forward strand). Ensembl gene ENSG00000108443.
Subcellular location: Synapse, synaptosome; Mitochondrion outer membrane; Mitochondrion; Nucleus (Isoform Alpha I); Cytoplasm; Cytoplasm (Isoform Alpha II)
Subcellular location (Human Protein Atlas): Nucleoplasm
Pathways (Reactome):
Signal Transduction: mTORC1-mediated signalling
Gene Ontology:
Molecular function: protein binding; protein kinase activity; protein serine kinase activity; protein serine/threonine kinase activity; protein serine/threonine/tyrosine kinase activity; ATP binding
Biological process: cellular response to growth factor stimulus; cellular response to nutrient; G1/S transition of mitotic cell cycle; negative regulation of apoptotic process; negative regulation of insulin receptor signaling pathway; negative regulation of TORC2 signaling; peptidyl-serine phosphorylation; positive regulation of mitotic cell cycle; positive regulation of mRNA splicing, via spliceosome; positive regulation of TORC1 signaling; positive regulation of translation; positive regulation of translational initiation; regulation of kinase activity; response to nutrient levels; TOR signaling; TORC1 signaling; cellular response to insulin stimulus; long-chain fatty acid import into cell; phosphatidylinositol-mediated signaling; signal transduction; cellular response to type II interferon; modulation of chemical synaptic transmission
Cellular component: mitochondrion; nucleoplasm; cytosol; cytoplasm; glutamatergic synapse; mitochondrial outer membrane; nucleus; synapse
Genetic constraint (gnomAD): Loss-of-function variants: 6 observed, 30.57 expected, observed/expected ratio (o/e) 0.2, 90% interval 0.11 to 0.39. The upper end of that interval is the gene's LOEUF score, 0.39, which puts it in group 1 of 6, group 1 being the genes least tolerant of losing a copy. Missense variants: 163 observed, 335.33 expected, observed/expected ratio (o/e) 0.49, 90% interval 0.43 to 0.55. Synonymous variants: 97 observed, 110.94 expected, observed/expected ratio (o/e) 0.87, 90% interval 0.74 to 1.03.
Gene-disease validity (ClinGen):
ClinGen rates the evidence that RPS6KB1 causes each of these diseases.
hypertrophic cardiomyopathy (autosomal dominant): Limited. A condition in which the myocardium is hypertrophied without an obvious cause.
Homologues: Orthologues: chimpanzee RPS6KB1 (100% identical), macaque RPS6KB1 (100% identical), pig RPS6KB1 (99% identical), rat Rps6kb1 (99% identical), dog RPS6KB1 (99% identical), mouse Rps6kb1 (99% identical), guinea pig RPS6KB1 (94% identical), rabbit RPS6KB1 (93% identical), tropical clawed frog rps6kb1 (91% identical), Drosophila melanogaster S6k (56% identical), Caenorhabditis elegans rsks-1 (53% identical), Caenorhabditis elegans R04A9.7 (35% identical), and 3 more. Paralogues in human: RPS6KB2 (64% identical), RPS6KA2 (43% identical), RPS6KA6 (43% identical), RPS6KA3 (42% identical), RPS6KA1 (42% identical), RPS6KA5 (40% identical), RPS6KA4 (38% identical).
Diseases named in the same sentence as RPS6KB1 in open-access papers:
RPS6KB1 is named in the same sentence as 360 diseases in open-access papers, as found by Europe PMC text mining. Sharing a sentence is not in itself a finding about the gene and the disease. The quoted sentences say what the papers report.
breast cancer (247 papers, 2004 to 2025). A primary or metastatic malignant neoplasm involving the breast. "The first clue regarding the involvement of S6K1 in breast cancer came from the identification that S6K1 (encoded by RPS6KB1) is localized on the chromosomal region 17q23, which is amplified in 20% of primary breast cancers." (PMID 32054043, 2020). "The RPS6KB1 gene is amplified and overexpressed in approximately 10% of breast carcinomas and has been found associated with poor prognosis." (PMID 15083183, 2004). "In addition, Rab7a silencing also caused reduced expression of RPS6KB1, which has been reported to be altered in breast cancer tissues." (PMID 29769411, 2019). "Using a single-gene mathematical model, we discovered approximately 560–680 genes out of 6000 exhibiting multistable expression states in each subpopulation, including key estrogen-receptor-positive breast cancer cell survival genes, such as RPS6KB1." (PMID 38791962, 2024). "It was found that the tandem duplication giving rise to RPS6KB1/VMP1 in breast cancer also leads to a duplication of miR-21." (PMID 38612567, 2024). "Of these genes, only RPS6KB1, VMP1, PPM1D and BCAS3 have been implicated in tumor development using clinical data from breast cancer patients." (PMID 34797887, 2021). "Of these genes and proteins, three are classically upregulated in breast cancer, and these are associated with poor prognosis in breast cancer: CCDN1/cyclin D1, PTPN11/SHP2, and RPS6KB1/S6K1." (PMID 33204396, 2020). "RPS6KB1 amplification (≥4 copies) has been reported in 10.7% of breast cancers, and gene gains (≥3 copies) have been reported in 21.4% of breast cancers." (PMID 32054043, 2020). "The chromosomal region 17q23 containing the p70S6K gene (RPS6KB1) is amplified in approximately 10% of all primary breast cancer cases, leading to p70S6K overexpression and this amplification is associated with poor prognosis." (PMID 27155197, 2016). "This fusion also has been reported in breast cancer and several cancer cell lines including HeLa S3; RPS6KB1 encodes the protein p70S6K that plays a key role in controlling the cell cycle, growth and survival." (PMID 26550473, 2015). "Amplification of the RPS6KB1 loci (Ribosomal protein S6 kinase beta-1) was described in other breast cancers as an oncogene event." (PMID 22496636, 2012). "Of these, 24 are nonsynonymous changes that occur in a diverse group of genes, including IRAK1 (possibly mutated in breast tumor B421) and RPS6KB1 (possibly mutated in BT474), which were previously identified as somatic mutations in breast cancer." (PMID 18364049, 2008). "The 17q23 region is one of the most highly amplified regions in breast cancer and RPS6KB1 is considered one of its target genes." (PMID 18652687, 2008). "Our results show for the first time the genome-wide transcriptional consequences of PI3K/mTOR pathway and RPS6KB1 inhibitions in breast cancer, suggesting novel downstream targets for PI3K/mTOR pathway and p70S6 kinase." (PMID 18652687, 2008). "The p70S6K dependent profiles were determined by siRNA silencing of RPS6KB1 in two breast cancer cell lines overexpressing p70S6K." (PMID 18652687, 2008). "The 70 kDa ribosomal protein S6 kinase (RPS6KB1), located at 17q23, is amplified and overexpressed in 10–30% of primary breast cancers and breast cancer cell lines." (PMID 18652687, 2008). "To identify downstream targets of p70S6K in breast cancer cells, we first examined gene expression alterations in RPS6KB1-suppressed BT-474 and MCF-7 breast cancer cell lines that normally show high-level expression of p70S6K." (PMID 18652687, 2008). "The RPS6KB1 gene is located at 17q23 and amplified in approximately 10% of all primary breast cancer cases." (PMID 15083183, 2004). "This novel S6K1 function might explain how tumors of breast cancer patients with RPS6KB1 gene amplification may present as radiation and chemotherapy resistant." (PMID 36189922, 2022).
breast cancer (continued). "Alternatively, breast cancer patients with low RPS6KB1 copy number might be hypersensitive to these treatments and will benefit the most." (PMID 36189922, 2022). "Moreover, breast cancer cells harboring RPS6KB1 gene amplification show increased resistance to several DNA damaging agents and S6K1 expression is associated with poor survival of breast cancer patients treated with chemotherapy." (PMID 36189922, 2022). "Thus, further studies should be performed to explore the role of PRKAA1 and RPS6KB1 in breast cancer development." (PMID 29769411, 2019). "Hence, RPS6KB1 may function both as a recurrent and promiscuous fusion gene partner in a subset of breast cancers." (PMID 23119097, 2012). "In the breast cancer cell line MCF-7, a fusion between exon 2 of RPS6KB1 and exon 11 of VMP1 was found." (PMID 38612567, 2024). "In this work, the authors described a RPS6KB1/VMP1 fusion transcript that is the product of a tandem duplication and is present in breast cancer samples." (PMID 38612567, 2024). "Subsequent studies showed that S6K1 and ERα constitute a positive feed-forward loop, the phosphorylated ERα by S6K1, which in turn promotes the transcription of RPS6KB1 to further mediate breast cancer cell proliferation." (PMID 38067394, 2023). "Two breast cancer cell lines harboring RPS6KB1 amplification (MCF7, BT474) were compared to two breast cancer cell lines with low S6K1 expression (HCC70, SKBR3) for sensitivity to chemotherapeutic agents." (PMID 36189922, 2022). "Previous studies revealed that both RPS6KB1 and RPS6KB2 exhibit amplifications or gene gains in breast cancer tissues." (PMID 35879299, 2022). "Here, we present a list of seven putative genes that are modulated by Rsv in breast cancer in the context of cotreatment with Doxo: HSP90AA1, CCND1, CDH1, ESR1, MAPK3, PTPN11, and RPS6KB1." (PMID 33204396, 2020). "This revealed several known kinase targets in breast cancer such as ERBB2, PAK1, RPS6KB1 and PTK2 (refs 16, 17), together with a new candidate kinase target, TLK2." (PMID 27694828, 2016). "In another recent study, Lamb and colleagues identified a 15-fold upregulation of an isoform of S6K (RPS6KB1) protein in CSCs-derived mammospheres from MCF-7 and T47D breast cancer cell lines." (PMID 27826244, 2016). "Mutation of PIK3R5 and other genes (i.e. PRKCZ, PTEN, RHEB and RPS6KB1) have altered PI3K signaling pathway, which is the central pathway for both colorectal and breast cancers." (PMID 27161113, 2016). "For example, a top hit in our screen, RPS6KB1, is downstream of mTOR and PI3K, two prominent signaling pathways in breast cancer with known direct inhibitors, rapamycin and LY294002, and that have been shown to sensitize cells to paclitaxel." (PMID 20576088, 2010). "We also compared the individual gene expression profiles between Ly294002- and rapamycin-treated and RPS6KB1-suppressed BT-474 and MCF-7 breast cancer cell lines to identify genes downstream of PI3K/mTOR/p70S6K pathway." (PMID 18652687, 2008). "Five breast cancer cell lines were treated with PI3K/mTOR pathway inhibitors, including two cell lines that were also inhibited with three RPS6KB1 siRNAs, since these two cell lines show a high-level expression of p70S6K." (PMID 18652687, 2008). "The microarray analyses showed that altogether 109 and 173 genes displayed over two-fold difference with at least two different RPS6KB1 siRNAs in BT-474 and MCF-7 breast cancer cell lines, respectively." (PMID 18652687, 2008). "Expression of p70S6K1 in different types of breast cancers is extensively studied, as the RPS6KB1 gene is located in the 17q23 chromosomal region that is amplified in 20% of breast cancers." (PMID 39749216, 2024). "Further studies showed that S6K1 and ERα constitute a positive feed-forward loop, where the phosphorylation of ERα by S6K1 promotes its activity, which in turn promotes transcription of RPS6KB1 to mediate breast cancer cell proliferation." (PMID 32054043, 2020).
breast cancer (continued). "This suggests that TLK2 is frequently co-amplified with RPS6KB1, but not with other known amplified genes in breast cancer such as ERBB2, MYC, CCND1, and so on." (PMID 27694828, 2016). "It has been observed that the breast cancer cell lines with an amplification of RPS6KB1 are more sensitive to rapamycin than cells with no amplification." (PMID 18652687, 2008). "Indeed, also in our study, the breast cancer cell lines BT-474, MCF-7 and MDA-361, which have an amplification of RPS6KB1, seemed to be sensitive to the rapamycin-induced G1 phase arrest." (PMID 18652687, 2008). "Therefore, breast cancer cell lines BT-474, MCF-7, MDA-361, MDA-436 and SK-BR-3 were treated with these inhibitors to compare transcriptional signatures responsive to both RPS6KB1 and PI3K/mTOR pathway inhibitions." (PMID 18652687, 2008). "One possibility is that RPS6KB1 is frequently co-amplified with TLK2, which may provide additional genetic background for the action of endogenously overexpressed TLK2 in breast cancer cells." (PMID 27694828, 2016). "The identification of S6K1 as a potential therapeutic target in oncology is supported by the fact that the S6K1 gene (RPS6KB1) is located at human chromosome 17q23, a region that is amplified in 20% of primary breast cancers as measured by comparative genomic hybridisation." (PMID 24072592, 2013).
Insulin resistance (172 papers, 2009 to 2026). Increased resistance towards insulin, that is, diminished effectiveness of insulin in reducing blood glucose levels. "We show that deletion of Rps6kb1 in POMC neurons leads to defective regulation of HGP, while deletion in AgRP neurons causes skeletal muscle insulin resistance." (PMID 25865886, 2015).
Obesity (104 papers, 2006 to 2026). Accumulation of substantial excess body fat. "RPS6KB1 is a key factor in protein synthesis and has been found to be involved in a variety of human diseases ranging from diabetes, obesity, hemangioma to cancer." (PMID 28792981, 2017). "In a high fat diet mice model, absence or knockdown of RPS6KB1 impaired the early adipocyte progenitor generation and attenuated the adipogenesis, indicating a critical role of RPS6KB1 in obesity." (PMID 28792981, 2017). "First, we identified gene sets related to the function of each obesity-related serum factor: HG/HI (Insr, Irs1, Rps6kb1, Slc2a4, Slc2a5, Slc2a1), TNF-α (Tnfrsf1a, Tradd, Traf2, Fadd), IL-6 (Il6ra, Il6st, Jak1), and fatty acids (PA, LA, Chol; Ffar1, Ffar4, Ppara, Pdk4, Pgc1a)." (PMID 37047207, 2023). "RPS6KB1 (an AMPK responsive gene for protein synthesis and cell growth), estrogen receptor α (encoded by the ESR1 gene) and its target gene GATA3, were significantly downregulated in rFNAs from premenopausal women with obesity." (PMID 34485137, 2021). "Furthermore, it has been demonstrated that RPS6KB1 is ribosomal protein S6 kinase, essential for protein translation and has an important role in a variety of metabolic diseases, such as obesity and diabetes." (PMID 32325903, 2020). "Similarly, it has been reported that the absence of Rps6kb1, another putative miR-200b/a/429 target, in mice protects against age- and diet-induced obesity." (PMID 27655719, 2016).
prostate carcinoma (71 papers, 2011 to 2025). A carcinoma that arises from epithelial cells of the prostate gland. "RPS6KB1 encodes ribosomal protein S6 kinase B1 which plays a key role in regulating protein translation and progression of hepatocellular carcinoma, prostate cancer and small cell lung cancer." (PMID 32212785, 2020). "Recent studies found that p-RPS6KB1 is upregulated in prostate cancer and that it plays an essential role in sensitization of radiation therapy." (PMID 37456776, 2023). "Meanwhile, suppressing RPS6KB1 activity by miR-195 inhibited prostate cancer invasion and migration, which provided a potential target for prostate cancer treatment." (PMID 33593435, 2021). "For RPS6KB1, knockdown of RPS6KB1 increased their sensitivity toward radiation-induced survival inhibition in prostate cancer cells." (PMID 32963532, 2020). "This gene inhibits hepatocellular carcinoma by regulating PHF19, regulates rectal cancer through CDK8, regulates osteosarcoma by inhibiting NKD1, regulates prostate cancer through Fra-1 or RPS6KB1." (PMID 28498798, 2017). "Moreover, EIF4EBP1 and RPS6KB1 showed a positive correlation with the catalytic subunit METTL3 in prostate cancer and contained candidate sites for m6A modifications (Supplementary Excel S6), suggesting m6A involvement in their translation." (PMID 33273988, 2020). "In prostate cancer (PCa) cells, a group of genes related to glucose metabolism such as those of the key glycolytic enzyme HK2, GLUT1, and ribosomal protein S6 kinase B1 (RPS6KB1) are positively correlated with the expression of EZH2." (PMID 32448308, 2020).